AFP (alpha fetoprotein)
Diseases named in the same sentence as AFP in open-access papers (continued):
Sharing a sentence is not in itself a finding about the gene and the disease.
anemia (continued). "Furthermore, anemia, malnutrition, PNI score, and AFP level were all improved mainly by a stable oral intake after bypass surgery." (PMID 33409765, 2021). "Further, tumor markers, such as CEA, AFP and CA 19-9 have been significantly higher in patients with CRC and anemia incomparison to patients with CRC without anemia." (PMID 35611243, 2022).
gastric adenocarcinoma (32 papers, 2009 to 2026). "Several studies have reported, that GPC3 is an oncofetal protein, which is associated with the alpha-fetoprotein-producing (AFP) hepatoid phenotype of gastric adenocarcinoma and gastric adenocarcinoma of enteroblastic differentiation." (PMID 31100935, 2019). "FU97 is a gastric adenocarcinoma cell line that also expresses alpha-fetoprotein, which represents a rare variant of gastric adenocarcinoma." (PMID 31231464, 2019). "In AFP producing gastric adenocarcinoma group, poor RSF and OS were associated with high levels of expression of XIAP (log rank, p=0.016 and p=0.013, respectively), IGF-Irβ (p=0.024 and p=0.028) and Autotaxin (p=0.034 and p=0.011)." (PMID 27057629, 2016). "In AFP producing gastric adenocarcinoma group, the risk scores were calculated based on 3 independent factors including XIAP, IGF-Irβ and TNM stage, as well as their corresponding regression coefficients." (PMID 27057629, 2016). "The patients with higher risk scores associated with poorer survival as compared with those with lower risk scores, suggesting 2 distinct subgroups in AFP producing gastric adenocarcinoma." (PMID 27057629, 2016). "Based on three independent prognostic factors, we established a risk model to stratify the AFP-producing gastric adenocarcinoma patients and demonstrated 2 subgroups in AFP-producing gastric adenocarcinoma." (PMID 27057629, 2016). "By using the risk scores, the patients with AFP producing gastric adenocarcinoma was able to classify into high or low risk groups, separated on 50% median of the risk scores." (PMID 27057629, 2016). "Successive studies concluded that regardless of whether there was a special pathological morphology, cases of positive AFP immunohistochemistry or elevated sAFP had a suggestive risk of progression, collectively referred to as "AFP-producing gastric adenocarcinoma"." (PMID 34706681, 2021). "This case report details the presentation of a 30-year-old female patient with gastric adenocarcinoma that metastasized to the ovaries, characterized by a significant elevation in serum AFP levels." (PMID 41800062, 2026). "The theory was confirmed by 19 AFP-producing gastric adenocarcinomas (AFPGA) gene analyses where multiple foci were microdissected and loss of heterozygosity (LOH) analysis was performed." (PMID 38817451, 2024). "Though some studies argued the predictive value of serum AFP, most previous studies have confirmed that the prognosis of even early gastric adenocarcinoma with elevated serum AFP is poor." (PMID 34706681, 2021). "Both the serum AFP level and immunohistochemical expression of can be used to indicate a poor prognosis for gastric adenocarcinoma." (PMID 34706681, 2021). "In this study, we collected gastric adenocarcinoma cases with definite sAFP levels and then analyzed their clinicopathological characteristics and immunohistochemical results of AFP, GPC3, and SALL4." (PMID 34706681, 2021). "Currently, AFP producing gastric adenocarcinoma is considered as a rare subtype of gastric adenocarcinoma." (PMID 27057629, 2016). "In conclusion, AFP producing gastric adenocarcinoma is a heterogeneous cancer with different clinical outcomes, biological behaviors and underlying molecular alterations." (PMID 27057629, 2016). "In an attempt to correlate protein expression with clinical behaviors and to understand the signaling pathways, we applied Protein Pathway Array technology to identify proteins altered in AFP-producing gastric adenocarcinoma." (PMID 27057629, 2016). "In the current study, potential protein markers were identified and cellular pathways involved in AFP-producing gastric adenocarcinoma were suggested." (PMID 27057629, 2016). "In univariate analyses of AFP-producing gastric adenocarcinoma group, higher TNM stage and increased expression of XIAP, IGF-Irβ and Autotaxin were found to be correlated with poor RFS and OS." (PMID 27057629, 2016).
gastric adenocarcinoma (continued). "A risk model based on the XIAP and IGF-Irβ expression levels can separate AFP producing gastric adenocarcinoma patients into 2 subgroups and each subgroup had a distinct set of signaling pathways involved." (PMID 27057629, 2016). "Compared with previous studies, this study investigated much more signaling related proteins simultaneously (a total of 286) in AFP-producing gastric adenocarcinoma." (PMID 27057629, 2016). "AFP producing gastric adenocarcinoma is a special subtype of gastric adenocarcinoma that should be treated separately." (PMID 27057629, 2016). "In conclusion, AFP producing gastric adenocarcinoma demonstrates aggressively clinical and biological behaviors." (PMID 27057629, 2016). "Alpha-fetoprotein (AFP) producing gastric adenocarcinoma is considered as a rare subtype of gastric adenocarcinoma." (PMID 27057629, 2016). "For example, ADAM-10 was up-regulated in AFP producing gastric adenocarcinoma tumor tissues with poor histology grade and distal location, while DPYD was down-regulated in the tumor tissues with moderate histology grade and without vascular invasion." (PMID 27057629, 2016). "AFP producing gastric adenocarcinoma is a rare group gastric adenocarcinoma with frequent liver metastasis and poor prognosis." (PMID 27057629, 2016). "Eleven differentially-expressed proteins were identified and several of them correlate with relapse-free survival (RFS) and overall survival (OS) of AFP producing gastric adenocarcinoma." (PMID 27057629, 2016). "The prevalence of AFP producing gastric adenocarcinoma has been reported to be 1.3∼6.3%, with high level of serum AFP being an independent prognostic factor." (PMID 27057629, 2016). "In the past years, the biological behavior and molecular characteristic of AFP-producing gastric adenocarcinoma has been studied." (PMID 27057629, 2016). "Eleven proteins were found to be differentially expressed in AFP-producing gastric adenocarcinoma in this study and these proteins play important roles in cell signaling pathways." (PMID 27057629, 2016). "Mean overall survival (OS) was 21.5 months (95% CI, 13.9-29.0 months) in AFP producing gastric adenocarcinoma group, compared with 34.5 months (95% CI, 27.4-41.7 months) in the AFP non-producing gastric adenocarcinoma group." (PMID 27057629, 2016). "Previous authors reported the occurrence of gastric adenocarcinoma with a high serum AFP level and synchronous hepatic metastasis." (PMID 22018031, 2011). "The authors described AFP-producing gastric adenocarcinomas with a high serum AFP level and synchronous hepatic metastasis." (PMID 22018031, 2011). "With definite diagnosis of AFP-producing hepatoid gastric adenocarcinoma metastatic to the liver, patient was then referred to Clinical Oncology Department where, in order to complete pretreatment evaluation, a thoracic-abdominal-pelvic CAT was requested." (PMID 19674468, 2009). "Therefore, in clinical practice, HAS should be highly suspected in patients with gastric adenocarcinoma with elevated AFP, and a pathological biopsy was performed as early as possible to obtain a definite diagnosis." (PMID 37161409, 2023). "These molecular differences could partly explain why some AFP gastric adenocarcinoma patients live longer." (PMID 27057629, 2016). "Those proteins and pathways could be potential clinical biomarkers and therapeutic targets in AFP-producing gastric adenocarcinoma." (PMID 27057629, 2016). "The previous reports showed that Ki-67, c-Met, vascular endothelial growth factor (VEGF), STAT3, hepatocyte growth factor and its receptor were highly expressed in AFP producing gastric adenocarcinoma tissues and cell lines as compared with AFP-negative gastric adenocarcinoma." (PMID 27057629, 2016). "However, how these factors and their associated signaling pathways regulate the aggressive behavior of AFP producing gastric adenocarcinoma remain to be fully established." (PMID 27057629, 2016).
gastric adenocarcinoma (continued). "In addition, the high level expression of XIAP and IGF-Irβ in gastric adenocarcinoma tissues was independent factors for poor prognosis in AFP producing gastric adenocarcinoma patients." (PMID 27057629, 2016). "Those factors play important roles in cell mitosis, proliferative activity, migration and tumor progression and they may potentially serve as molecular markers of AFP producing gastric adenocarcinoma." (PMID 27057629, 2016). "Two proteins were down-regulated in AFP producing gastric adenocarcinoma, including ASC-R and BID." (PMID 27057629, 2016). "In addition, a few other tumors including gastric adenocarcinoma can also produce AFP." (PMID 27057629, 2016). "Therefore, a high level expression of XIAP in gastric adenocarcinoma cells, which reduces cancer cell apoptosis, could be a reason for the poor prognosis in the AFP-producing gastric adenocarcinoma patients." (PMID 27057629, 2016). "AFP and hepatocyte antigens can be utilized to differentiate HAS from hepatocellular and common adenocarcinoma of the stomach." (PMID 38831124, 2024). "Both the serum AFP level and immunohistochemical expression of AFP/GPC3/SALL4 can be used to indicate a poor prognosis for gastric adenocarcinoma." (PMID 34706681, 2021). "Among 20 pathways altered in gastric adenocarcinoma, the PI3k, PTEN, IL-8 and growth hormone signaling pathways were affected most, suggested that they play important roles in pathogenesis of AFP producing gastric adenocarcinoma." (PMID 27057629, 2016). "In the previous work, HAS patients assumed worse prognosis than gastric adenocarcinoma regardless of serum AFP level." (PMID 36647059, 2023). "We collected 421 consecutive non-neoadjuvant surgically or endoscopically resected gastric adenocarcinoma patients with serum AFP results before surgery (group A)." (PMID 34706681, 2021). "We also collected 12 non-resected gastric adenocarcinoma patients with serum AFP ≥ 7 ng/mL before treatment (group B)." (PMID 34706681, 2021). "Intriguingly, the common gastric adenocarcinomas express the oncofetal proteins GPC3 and AFP." (PMID 31100935, 2019). "Kaplan-Meier survival analyses showed that AFP non-producing gastric adenocarcinoma group correlated with significant favorable RFS and OS (log-rank p=0.030 and p=0.012, respectively)." (PMID 27057629, 2016). "Mean relapse free survival (RFS) was 9 months (95%CI: 6.6-11.6 months) in the AFP producing gastric adenocarcinoma group, compared with 30 months (95% CI: 6.6-53.4months) in the AFP non-producing gastric adenocarcinoma group (log-rank p=0.030)." (PMID 27057629, 2016). "In the current study, we investigated the expression of 286 functionally important proteins and phosphoproteins in AFP producing and AFP non-producing gastric adenocarcinoma using high-throughput protein pathway array (PPA)." (PMID 27057629, 2016). "In AFP producing gastric adenocarcinoma group, 20 patients had liver metastasis [62.5% (20/32)] compared with 5 in AFP non-producing gastric adenocarcinoma group results [11.1% (5/45)] (p=0.001)." (PMID 27057629, 2016). "In contrast, in AFP non-producing gastric adenocarcinoma group, none of 11 differentially expressed proteins, XIAP IGF-Irβ and Autotaxin included, were demonstrated association with RSF and OS." (PMID 27057629, 2016). "An obvious difference in protein expression were observed between AFP producing and AFP non-producing gastric adenocarcinomas, although 3 samples were misclassified, suggesting that non-AFP producing gastric adenocarcinoma is a distinct entity." (PMID 27057629, 2016). "Using the Protein Pathway Array, 11 of out of 286 proteins tested were found to be differentially expressed between AFP producing (n=32) and AFP non-producing (n=45) gastric adenocarcinoma tissues." (PMID 27057629, 2016). "Compared with AFP non-producing gastric adenocarcinoma, our study and other previous studies showed that AFP producing gastric adenocarcinoma is more aggressive and prone to liver metastasis." (PMID 27057629, 2016).
gastric adenocarcinoma (continued). "More importantly, our study showed that the high level expression of XIAP and IGF-Irβ were independent prognostic factors and correlated with poor survival in AFP producing gastric adenocarcinoma patients but not in the AFP non-producing patients." (PMID 27057629, 2016). "Compared with AFP non-producing gastric adenocarcinoma, previous studies, including our study, showed that AFP producing gastric adenocarcinoma is more aggressive with high incidence of liver metastasis and poor prognosis." (PMID 27057629, 2016). "In AFP producing gastric adenocarcinoma group, 27 patients had relapsed [84.4% (27/32)] compared with 28 in AFP non-producing gastric adenocarcinoma group [62.2% (28/45)] (p=0.029)." (PMID 27057629, 2016). "Additional features, such as a high expression rate of vascular endothelial growth factor (VEGF) and its isoform VEGF-C, were noticed in AFPGA when immunohistochemical analysis was done in 26 patients with AFPGA compared to patients with gastric adenocarcinomas without AFP production." (PMID 38817451, 2024). "However, to our knowledge, dysregulation of cyclin D1, RANKL, LSD1, Autotaxin, Calpain2, XIAP, IGF-Irβ, ASC-R and BID in AFP producing gastric adenocarcinoma has not been reported before." (PMID 27057629, 2016). "Furthermore, since AFP-producing gastric adenocarcinoma is not homogeneous in terms of clinical outcome and molecular characteristics, it is critical to identify biomarkers that can further subcategorize AFP-producing gastric adenocarcinoma." (PMID 27057629, 2016). "The majority of our cohort consisted of conventional gastric adenocarcinomas, in which AFP was seldom elevated; thus, the absence of a TNF-α–AFP relationship simply reflects that AFP was not a prevalent tumor marker in these patients." (PMID 40299527, 2025). "Pathological morphology serves as the cornerstone for diagnosis, often accompanied by elevated alpha-fetoprotein (AFP) levels, nonspecific clinical symptoms, and imaging features reminiscent of gastric adenocarcinoma (GA)." (PMID 38993642, 2024). "Similarly, the AFP-producing gastric adenocarcinomas featured much more frequent VEGF-C expression and higher micro-vessel density than AFP non-producing gastric adenocarcinomas." (PMID 27057629, 2016).
fibrosis (30 papers, 2008 to 2025). the formation of excess fibrous connective tissue in an organ or tissue in a reparative or reactive process. "Semi-annual ultrasound and alpha-fetoprotein for all people with chronic liver disease with fibrosis ≥ F3 of any cause (including HCV infection) or with any fibrosis for patients with HBV." (PMID 34838115, 2021). "Elevated AFP levels and Fibrosis score F1 were significantly associated with increased risk of mortality (P < 0.05)." (PMID 30656831, 2019). "Multivariate analysis showed that higher AJCC stage, lower tumor grade, and higher liver fibrosis score were associated with a higher incidence of increased AFP levels in these three race groups, although the ORs were different among them." (PMID 31517445, 2019). "It covers a range of variables such as age, liver biochemical markers (ALT, AST, Albumin, GGT, T.Bil), metabolic indicators (BMI, HbA1C, FBS, TG, TC, LDL, HDL), and markers of liver health or disease (AFP, PLTs, Fibrosis Stages, Sonography)." (PMID 41026784, 2025). "A Japanese study also found that low baseline levels of serum AFP are assocJiated with fibrosis regression in hepatitis C virus (HCV) infected patients who achieved sustained virological response (SVR)." (PMID 37241155, 2023). "Our findings suggest that Differentiation, Tumor size, AFP, and Fibrosis are the most relevant predictors of prognosis." (PMID 36717904, 2023). "All our data were confirmed in a multivariate statistical analysis of the different prognostic factors in both SVR and NR patients including Fibrosis score, Histology Activity Index (HAI), Alpha-Fetoprotein (AFP) levels, and CCR5 alleles." (PMID 24403912, 2013). "There was no statistical difference comparing different variables regarding age, sex, total bilirubin, alpha-fetoprotein, serum creatinine, count or HBV DNA between patients with minimal fibrosis versus those with advanced fibrosis as indicated by liver biopsy (untabulated data)." (PMID 27785271, 2014).
choriocarcinoma (29 papers, 2010 to 2025). An aggressive malignant tumor arising from trophoblastic cells. "Various serum tumor markers (β-hCG, AFP and CA-125) are also useful in the differential diagnosis of choriocarcinoma." (PMID 21108779, 2010). "The determination of serum tumor markers HCG and AFP may be helpful in the diagnosis of choriocarcinoma because they are elevated in about 80% of cases." (PMID 35710558, 2022). "Both YST cases demonstrated elevation in AFP, one of which was also notable for elevated HCG as well; one choriocarcinoma demonstrated elevated HCG." (PMID 36995447, 2023). "β-HCG is significantly high in pure choriocarcinoma (> 1000 IU/L, normal range is < 2 mIU/mL) and choriocarcinoma does not produce AFP." (PMID 39099693, 2024). "AFP and β-HCG are secreted by nonseminomatous tumours, YST and syncytiotrophoblast of choriocarcinoma, whereas LDH is also secreted by SE." (PMID 29262668, 2017).